ENSG00000276019
Gene: Miscellaneous RNA gene on chromosome 6 (8,653,558 to 8,653,797, forward strand). Ensembl gene ENSG00000276019.
Gene Ontology:
Biological process: regulation of gene expression
Cellular component: ribosome